SCML1 (Scm polycomb group protein like 1)
Description:
Putative Polycomb group (PcG) protein. PcG proteins act by forming multiprotein complexes, which are required to maintain the transcriptionally repressive state of homeotic genes throughout development. May be involved in spermatogenesis during sexual maturation (By similarity).
Tractability: PROTAC: ubiquitination databases record sites on it.
Gene: Protein-coding gene on chromosome X (17,737,115 to 17,754,988, forward strand). Ensembl gene ENSG00000047634.
Subcellular location: Nucleus
Subcellular location (Human Protein Atlas): Nucleoplasm
Gene Ontology:
Molecular function: chromatin binding; histone binding
Biological process: negative regulation of DNA-templated transcription
Cellular component: nucleus
Homologues: Orthologues: chimpanzee SCML1 (92% identical), macaque SCML1 (65% identical), Drosophila melanogaster Scm (19% identical), zebrafish phc1 (14% identical), Drosophila melanogaster l(3)mbt (13% identical), Drosophila melanogaster Sfmbt (9% identical), Caenorhabditis elegans lin-61 (9% identical), Caenorhabditis elegans mbtr-1 (7% identical). Paralogues in human: SCML2 (28% identical), SCMH1 (26% identical), SCML4 (22% identical), SFMBT1 (20% identical), SFMBT2 (18% identical), PHC1 (14% identical), PHC2 (13% identical), PHC3 (13% identical), L3MBTL3 (12% identical), L3MBTL4 (12% identical), MBTD1 (12% identical), L3MBTL2 (12% identical), and 6 more.
Diseases named in the same sentence as SCML1 in open-access papers:
SCML1 is named in the same sentence as 7 diseases in open-access papers, as found by Europe PMC text mining. Sharing a sentence is not in itself a finding about the gene and the disease. The quoted sentences say what the papers report.
lung carcinoma (7 papers, 2019 to 2025). "For instance, circNOL10 interacts with SCML1, inhibiting its protein ubiquitination and affecting mitochondrial function, thereby influencing lung cancer progression." (PMID 40535798, 2025). "CircNOL10 retarded the proliferation and promoted the apoptosis of lung cancer cells by enhancing the transcriptional regulatory effect of sex comb on midleg-like 1 (SCML1) on the humanin (HN) polypeptide family." (PMID 35127685, 2022). "circNOL10 interacted with sex comb on midleg-like 1 (SCML1) to prevent its ubiquitination, and promoted the SCML1 mediated transcriptional regulation of the HN family to inhibits lung cancer development." (PMID 33537235, 2020). "We constructed SCML1‐silencing and overexpression vectors, and circNOL10 reporter gene vectors and co‐transfected them into lung cancer cells." (PMID 30693177, 2019). "SCML1 was downregulated in lung cancer cells (H460 and A549) compared with control BEAS‐2B cells, as shown by western blot and confirmed by immunocytochemistry." (PMID 30693177, 2019). "This study investigates the functions and molecular mechanisms of circNOL10 in the development of lung cancer and reveals its involvement in the transcriptional regulation of the HN polypeptide family by SCML1." (PMID 30693177, 2019). "All these results suggested that circNOL10 inhibited SCML1 ubiquitination to increase its expression in lung cancer cells." (PMID 30693177, 2019). "A previous research revealed that circNOL10expression was reduced in lung cancer tissues and cells, and circNOL10 overexpression repressed cell proliferation and induced apoptosis through transcriptional regulation of the HN polypeptide family by SCML1." (PMID 33397365, 2021). "Furthermore, circNOL10 promoted expression of the transcription factor SCML1 and further induced transcription of the HN polypeptide family in lung cancer." (PMID 30693177, 2019). "Furthermore, we showed that circNOL10 inhibited lung cancer by enhancing transcriptional regulation of the HN polypeptide family by SCML1." (PMID 30693177, 2019). "Together with the fact that SCML1 was downregulated in cancer cells, we hypothesized that ubiquitination was involved in regulating the expression of SCML1 in lung cancer cells." (PMID 30693177, 2019). "In lung cancer, circ-NOL10 increases the expression of transcription factor sex comb on midleg‐like 1 (SCML1) by preventing transcription factor ubiquitination and consequently alters the regulation of the humanin polypeptide family by SCML1." (PMID 37587156, 2023).
cancer (4 papers, 2019 to 2025). A tumor composed of atypical neoplastic, often pleomorphic cells that invade other tissues. "This leads to the expression of genes associated with β-catenin activation, which supports cancer progression, while circ-NOL10 inhibits cancer development by promoting the expression of SCML1 by inhibiting transcription factor ubiquitination." (PMID 40002172, 2025).
SCML1 also shares sentences with these, for which no sentence is quoted: Azoospermia (1 paper); cryptorchidism (1); Intellectual disability (1); malaria (1); polycystic ovary syndrome (1).